CFTR (CF transmembrane conductance regulator)
Diseases named in the same sentence as CFTR in open-access papers (continued):
Sharing a sentence is not in itself a finding about the gene and the disease.
cystic fibrosis (continued). "In particular, targeting of microRNAs involved in the repression of the expression of the cystic fibrosis transmembrane conductance regulator (CFTR) gene, which is defective in cystic fibrosis, is a key step in the development of new types of treatment protocols." (PMID 32260566, 2020). "Several other protein targets, including human coagulation FXa and human CFTR, were identified and characterized as a target for this PLA2, showing its anticoagulant or anti-cystic fibrosis activity." (PMID 33202772, 2020). "Different miRNAs that have been found to be increased in the primary bronchial epithelial cells of cystic fibrosis patients can reduce CFTR expression, either by direct (miR-145-5p, miR-223-3p, miR-494-3p, miR-509-3p, miR-101-3p) or by indirect (miR-138-5p) interactions." (PMID 32260566, 2020). "CF pathophysiology results from variants in the cystic fibrosis transmembrane conductance regulator (CFTR) gene, which lead to absent or dysfunctional CFTR protein expression." (PMID 32973772, 2020). "Cystic fibrosis and isolated CBAVD are autosomal recessive and are recognized as cystic fibrosis transmembrane conductance regulator (CFTR)‐related diseases." (PMID 33071633, 2020). "A huge success story in the late ‘80s was the cloning (identification) of the cystic fibrosis gene, CFTR (cystic fibrosis transmembrane conductance regulator)." (PMID 32817613, 2020). "Cystic fibrosis (CF, OMIM 219700) is a monogenetic autosomal recessive condition caused by biallelic pathogenic variants in the Cystic Fibrosis Conductance Transmembrane Regulator (CFTR) gene." (PMID 33172004, 2020). "The airway epithelium contains ionocytes, a rare cell type with high expression of Forkhead Box I1 (FOXI1) transcription factor and Cystic Fibrosis Transmembrane conductance Regulator (CFTR), a chloride channel that is defective in cystic fibrosis." (PMID 32933106, 2020). "For example, inhibiting NMD by knocking down NMD factor expression in cultured epithelial cells from cystic fibrosis patients increases the abundance of PTC-containing CFTR mRNA and restores greater CFTR protein function than with readthrough approaches alone." (PMID 32737261, 2020). "In cystic fibrosis, the lack of a functioning CFTR protein, due to CFTR gene variants, results in increased susceptibility to lung infections and pancreatic insufficiency." (PMID 31118097, 2019). "High throughput screening and lead optimization have led to the successful introduction of FDA-approved small molecular compounds that modulate the biology of the cystic fibrosis transmembrane conductance regulator (CFTR) for the treatment of cystic fibrosis patients." (PMID 31413336, 2019). "In cystic fibrosis, impaired immune cell responses, driven by the dysfunctional CF transmembrane conductance regulator (CFTR) gene, may determine the disease severity but clinical heterogeneity remains a major therapeutic challenge." (PMID 31118097, 2019). "Newborn screening (NBS) for cystic fibrosis not only identifies infants with a diagnosis of CF, but also those with an uncertain diagnosis of cystic fibrosis, i.e. CF transmembrane conductance regulator (CFTR)-related metabolic syndrome (CRMS) or CF screen positive inconclusive diagnosis (CFSPID)." (PMID 31640630, 2019). "An example is a deletion in the cystic fibrosis transmembrane conductance regulator (CFTR) gene that removes one amino acid (phenylalanine) at position 508, which arrests protein function and leads to cystic fibrosis (Mullaney, Mills, Pittard, & Devine, 2010)." (PMID 30565766, 2019). "Available CFTR modulators provide no therapeutic benefit for cystic fibrosis caused by many loss-of-function mutations in the cystic fibrosis transmembrane conductance regulator (CFTR) chloride channel, including N1303K." (PMID 31776420, 2019).
cystic fibrosis (continued). "Cystic fibrosis is a genetic disease affecting today nearly 70,000 patients worldwide and characterized by a hypersecretion of thick mucus difficult to clear arising from the defective CFTR protein." (PMID 31921811, 2019). "Cystic fibrosis transmembrane conductance regulator (CFTR) is a unique member of the ATP-binding cassette (ABC) transporters family that acts as a cyclic adenosine monophosphate (cAMP)-regulated anion channel mediating chloride/bicarbonate transport across epithelia." (PMID 31321000, 2019). "The mutation of cystic fibrosis transmembrane conductance regulator (CFTR) can modify the physical and chemical properties of saliva, which in turn can affect the oral microflora and oral health in patients with cystic fibrosis." (PMID 31847106, 2019). "In Cystic Fibrosis, reduced transepithelial chloride (Cl−) and bicarbonate (HCO3−) ion transport through the dysfunctional cystic fibrosis transmembrane conductance regulator (CFTR) renders the airway vulnerable to dehydration and reduces the ASL pH." (PMID 29391451, 2018). "Cystic fibrosis is an autosomal recessive disorder, whose defect is found in thechromosome that codify the protein Cystic Fibrosis Transmembrane Conductance Regulator(CFTR)." (PMID 29412427, 2018). "Next we assessed whether the delayed apoptosis in CF was related to decreased cystic fibrosis transmembrane conductance regulator (CFTR) function in neutrophils." (PMID 28916704, 2018). "In cystic fibrosis it may soon be possible to test several corrector drugs that improve the folding and functional expression of mutant cystic fibrosis transmembrane conductance regulator (CFTR) prospectively using cells from a patient to find the one that is best for that individual." (PMID 30618775, 2018). "Cystic fibrosis transmembrane conductance regulator (CFTR), the culprit behind the genetic disease cystic fibrosis, is a phosphorylation-activated, but ATP-gated anion channel." (PMID 30596737, 2018). "At one extreme, only the highest level results of newborn screening might be stored, e.g., “no cystic fibrosis-associated CFTR allele found”, while at the other extreme a complete list of all variants or each individual’s entire exome or whole genome sequence might be stored." (PMID 28222731, 2017). "To date, >2,000 mutations have been identified in the CFTR gene (see the Hospital for Sick Children in Toronto Cystic Fibrosis Mutation Database), although the vast majority are very rare and not all lead to CF." (PMID 28087700, 2017). "The cystic fibrosis transmembrane conductance regulator (CFTR) is an N-glycosylated transmembrane protein with anion channel activity that permeates chloride and bicarbonate at the apical surface of secretory epithelia of the airways, intestine, pancreas, and exocrine glands." (PMID 28067262, 2017). "Mutations in the cystic fibrosis transmembrane conductance regulator (CFTR) gene cause cystic fibrosis and are associated with congenital bilateral absence of the vas deferens (CBAVD), which is the major cause of infertility in male patients with CF." (PMID 28384194, 2017). "Cystic fibrosis is the most common lethal genetic disorder of childhood in the Caucasian population and is due to recessive mutations in ABCC7, the gene encoding the CF transmembrane conductance regulator (CFTR)." (PMID 29222447, 2017). "The eccrine sweat gland is a near-ideal organ for assessing the function of CFTR—the anion channel that causes cystic fibrosis when absent or defective." (PMID 27768743, 2016). "Despite the fact that CFTR-deficient mouse model is considered of limited interest in the field of cystic fibrosis as it does not reproduce and develop the full CF phenotype." (PMID 27468800, 2016). "The phytochemical curcumin may improve translocation of the cystic fibrosis transmembrane regulatory (CFTR) protein in lung epithelium and therefore be helpful in the treatment of cystic fibrosis symptoms." (PMID 29124231, 2015).
cystic fibrosis (continued). "The fundamental physiologic issue in CF patients is that they cannot produce normal sweat, digestive fluids or mucus due to a defective transport protein, the cystic fibrosis transmembrane conductance regulator (CFTR)." (PMID 27417354, 2015). "Notably, both “mutations”- and “acquired”- CFTR (Cystic Fibrosis Transmembrane Conductance Regulator) dysfunction (COPD) are known to be associated with pathogenesis of chronic obstructive lung disease." (PMID 25794013, 2015). "Cystic fibrosis is a recessive genetic disorder caused by mutations in the cystic fibrosis transmembrane conductance regulator (CFTR) gene, rendering the protein non-functional." (PMID 26600426, 2015). "Diagnosis of CF is based on clinical manifestations plus sweat chloride tests, transepithelial nasal potential difference (NPD) measurements, or mutation analysis in cystic fibrosis transmembrane conductance regulator (CFTR) gene." (PMID 25071991, 2014). "Cystic Fibrosis is the most frequent recessive disease in Caucasian populations and is caused by mutations in the CFTR gene leading to the absence or the lack of function of this ABC transporter-class ion channel, which transports chloride and bicarbonate." (PMID 24223826, 2013). "Pharmacological chaperones for CF are predicted to be specific for the cystic fibrosis transmembrane conductance regulator (CFTR) and not correct other mutant proteins unless they share structural similarity with CFTR." (PMID 23316740, 2013). "Mutations in CFTR are known to result in multiple conditions, ranging from classic cystic fibrosis to monosymptomatic diseases such as congenital absence of the vas deferens, pancreatitis, or chronic bronchiectasis." (PMID 23343000, 2013). "Our results also indicate that that IGF-1 selectively increases CFTR protein expression and CFTR-mediated chloride transport in a cell line model, CFBE cells (the bronchial epithelial cell line from cystic fibrosis patients)." (PMID 23555857, 2013). "Although there is no doubt that etiology of CF is directly associated with the mutation in the cystic fibrosis transmembrane conductance regulator (CFTR) gene, it is very difficult to connect the disease clinical course with the type of mutation." (PMID 23343370, 2013). "Cystic fibrosis is the most common genetic disease among Caucasians, and accordingly the cystic fibrosis transmembrane conductance regulator (CFTR) protein has perhaps the best characterized disease mutation spectrum with more than 1,500 causative mutations having been identified." (PMID 22879944, 2012). "Our previous study has shown that spiperone, a known antipsychotic drug, activates CaCCs and stimulates Cl− secretion in polarized human non-CF and CF airway epithelial cell monolayers in vitro, and in Cystic Fibrosis Transmembrane Conductance Regulator (CFTR) knockout mice in vivo." (PMID 21765932, 2011). "Variability in cystic fibrosis lung disease is partially due to non-CFTR genetic modifiers." (PMID 21998660, 2011). "Evaluation of cystic fibrosis transmembrane conductance regulator (CFTR) functional activity to assess new therapies and define diagnosis of cystic fibrosis is cumbersome." (PMID 21811577, 2011). "Recently, aberrant miRNA expression has been observed in Cystic Fibrosis, an autosomal-recessive genetic disorder caused by mutations in the CFTR gene, in which a genotype-phenotype correlation is not always found." (PMID 22028919, 2011). "The mutation in the cystic fibrosis transmembrane conductance regulator (CFTR) gene results in CF." (PMID 20868490, 2010). "Mutation of the cystic fibrosis transmembrane-conductance regulator (CFTR) causes cystic fibrosis but not all CF aspects can easily be explained by deficient ion transport." (PMID 20644644, 2010). "Our data supports the view that in cystic fibrosis patients with ΔF508-mutation, the absence of CFTR from lipid rafts or the cell surface results in chronic inflammation and lung disease." (PMID 19247502, 2009).
cystic fibrosis (continued). "Therefore, we took advantage of the CFTR (cystic fibrosis transmembrane conductance regulator) null mouse (CF mouse), which has constitutively elevated expression levels of the Reg3α, PAP/Reg3β and Reg3γ genes." (PMID 16700916, 2006). "It has been suggested that low μM concentrations of S-nitrosoglutathione (GSNO), an endogenous bronchodilator, may promote maturation of the defective cystic fibrosis transmembrane conductance regulator (CFTR)." (PMID 17022806, 2006). "Here, we evaluated the in vitro therapeutic potential of PS-L in macrophages from people with cystic fibrosis (pwCF), either under therapeutic regimen or not with CFTR modulator therapy Elexacaftor/Tezacaftor/Ivacaftor (ETI)." (PMID 41685327, 2026). "The annual reports of the cystic fibrosis registry show that even the introduction of CFTR modulators did not lead to a significant reduction in incidence." (PMID 41472799, 2025). "Lastly, snRNA-H/ACA box snoRNA fusions (U>Ψ snRNAs) increase targeted RNA pseudouridylation without DKC1 overexpression, facilitating improved CFTR rescue from nonsense-mediated mRNA decay in a cystic fibrosis human bronchial epithelial cell model." (PMID 40968292, 2025). "Correction of CFTR function to levels seen in individuals without cystic fibrosis early in life has the best potential to restore normal physiology and prevent disease development or progression, or both." (PMID 39756424, 2025). "As such, many cystic fibrosis patients could develop cystic fibrosis-related diabetes (CFRD) exhibiting insulin insufficiency, a significant extra-pulmonary comorbidity associated with the CF transmembrane conductance regulator (CFTR)." (PMID 40625684, 2025). "Surpassing earlier CFTRm treatments, the triple combination significantly improves respiratory symptoms (assessed by cystic fibrosis questionnaire revised (CFQ-R) respiratory domain), lung function (assessed by ppFEV1), and CFTR activity (assessed by sweat chloride concentration)." (PMID 41377908, 2025). "Some people with cystic fibrosis have genotypes that are not currently approved for CFTR modulator treatment, including with elexacaftor–tezacaftor–ivacaftor." (PMID 39756424, 2025). "CFTR variants was the main pathogenic cause of congenital bilateral absence of the vas deferens (CBAVD) and cystic fibrosis." (PMID 39757988, 2025). "In this study, we have shown, using A. fumigatus reference strains and strains isolated from patients with cystic fibrosis, that CFTR modulators have no discernible impact on initial conidia growth in vitro." (PMID 40736245, 2025). "Accumulating evidence indicates that CFTR modulators represent a paradigm-shifting therapeutic breakthrough in cystic fibrosis, rather than merely one of several available treatment options." (PMID 40364218, 2025). "Nevertheless, ceiling effects may be particularly relevant in our CF population where the introduction of cystic fibrosis transmembrane conductance regulator (CFTR) modulators has already significantly improved the lung function in those eligible and with access to these therapies." (PMID 40908142, 2025). "ASL depletion due to deficient cystic fibrosis transmembrane conductance regulator (CFTR)-mediated anion/fluid secretion plays an important role in the pathogenesis of mucociliary dysfunction and chronic muco-obstructive lung disease in patients with cystic fibrosis." (PMID 41381809, 2025). "Cystic fibrosis is a genetic disease resulting in defective or absent CF transmembrane conductance regulator (CFTR) protein." (PMID 40368426, 2025). "As evidenced by recent publication, a 35-year-old man with stable cystic fibrosis, not on CFTR modulators, was found to have ALK-translocated lung cancer after presenting with an assumed bacterial exacerbation." (PMID 40563468, 2025). "Repeated nebulisation of non-viral CFTR gene therapyin patients with cystic fibrosis: a randomised, double-blind, placebocontrolled,phase 2b trial." (PMID 40297296, 2025).
cystic fibrosis (continued). "Previous studies suggest that CFTR is responsible for glutathione transport, which could explain the reduced GSH levels observed in the airways of patients with cystic fibrosis." (PMID 40563468, 2025). "Despite the increased transduction efficiency of respiratory epithelial cells and the enhanced expression level of the CFTR gene in vivo in animal models using mucolytics, these agents have not been used in clinical trials for cystic fibrosis gene therapy." (PMID 39765719, 2024). "In cystic fibrosis, TRPV1 activation could improve CFTR function and cough effectiveness, while β2AR stimulation increases mucociliary clearance and favors bronchodilation." (PMID 39408565, 2024). "While gene therapy in cystic fibrosis has had mixed results, it should be noted that small molecule regulators of the CFTR gene have proven that nucleotide delivery is not the only approach to modify gene expression in rare diseases." (PMID 38247731, 2024). "Also, given advancements in CF care and widespread use of cystic fibrosis transmembrane conductance regulator (CFTR) modulator therapy, pwCF are increasingly unable to routinely expectorate sputum and are presenting less often to clinic or with pulmonary exacerbations." (PMID 39148848, 2024). "Highly effective cystic fibrosis transmembrane conductance regulator (CFTR) modulator therapy (HEMT), including elexacaftor/tezacaftor/ivacaftor (ETI), is now approved for more than 90% of adults with the genetic disorder cystic fibrosis." (PMID 38564694, 2024). "Helper-dependent adenoviral vectors, lacking viral genes, enable long-term CFTR gene expression with minimal immune response, making them promising for cystic fibrosis therapy." (PMID 39765719, 2024). "Inflammation, acinar atrophy, and ductal hyperplasia drive pancreatic remodeling in newborn cystic fibrosis ferrets lacking a functional cystic fibrosis conductance regulator (CFTR) channel." (PMID 39687022, 2024). "CF is caused by mutations in the cystic fibrosis transmembrane conductance regulator (CFTR) gene, resulting in impaired pancreatic function and, as a result, reduced intestinal absorption of lipids and fat-soluble vitamins, particularly in patients with CF developing pancreatic insufficiency." (PMID 38229125, 2024). "Based on supporting results, we suggest that inflammation in the COVID-19 airway may be initiated by inhibition of CFTR signaling by SARS-CoV-2 spike protein, thus inducing a cystic fibrosis-like proinflammatory clinical phenotype." (PMID 39043712, 2024). "Three distinct pharmacological corrector types (I, II, III) with different binding sites and additive behavior only partially rescue the F508del-cystic fibrosis transmembrane conductance regulator (CFTR) folding and trafficking defect observed in cystic fibrosis." (PMID 38427726, 2024). "However, if sweat chloride is normal but the baby has two CFTR variants at least one of which has unclear phenotypic consequences, or sweat chloride is intermediate and the baby has one or no CFTR variants, they are said to have ‘cystic fibrosis screen positive, inconclusive diagnosis’ (CFSPID)." (PMID 38550936, 2023). "In contrast to ENaC, CFTR (ion transporter defective in cystic fibrosis) is located on the non-cilial cell surface." (PMID 38123150, 2023). "Many babies with CFSPID will not become unwell, but some will develop features of cystic fibrosis or a CFTR-related disorder at some point in the future." (PMID 38550936, 2023). "A population of colorectal cancer patients with no known relationship to cystic fibrosis expresses reduced levels of CFTR in their tumors." (PMID 36765944, 2023). "Cystic Fibrosis is a rare disease with autosomal recessive transmission, characterised by a lack of synthesis of the CFTR channel protein, and multi-organ clinical symptoms mainly affecting the respiratory tract with recurrent pulmonary exacerbations." (PMID 37957647, 2023).